LEP (leptin)
Diseases named in the same sentence as LEP in open-access papers (continued):
Sharing a sentence is not in itself a finding about the gene and the disease.
Obesity (continued). "Yet in our study, plasma cytokine levels were unaffected by dietary treatments along with non-fasting glucose and leptin and adiponectin concentrations, although we observed trends toward an “obesity phenotype”." (PMID 35187037, 2022). "IR is not related to leptin and adiponectin levels, however leptin and adiponectin levels correlated well with BMI in hypothyroid children and adolescents with obesity." (PMID 35501770, 2022). "Leptin resistance is induced by HFD and is related to obesity and T2D." (PMID 34949748, 2022). "The male, but not female offspring of rat fathers with HFD-induced obesity had higher body weights and leptin levels." (PMID 35197931, 2022). "For example, leptin is secreted by adipose tissue and is thought to be a key peptide in reducing food intake based on the extreme obesity that develops in the absence of leptin signaling." (PMID 34713962, 2022). "Moreover, mRNA expressions of obesity-related factors (GLUT4 and adiponectin) were increased after HK-LRCC5314 treatment, whereas leptin levels were decreased." (PMID 34949748, 2022). "Leptin resistance, in which the activation of its receptors at the central level no longer occurs correctly, is observed in obesity." (PMID 36512575, 2022). "The interaction effect of insulin resistance and serum Mg2+ with obesity markers BMI and Log10 Leptin were not significant after adjusting for confounders." (PMID 35440685, 2022). "In general, circulating leptin levels tend to be higher among females with and without obesity compared to their male counterparts." (PMID 35654771, 2022). "Human studies have observed that in subjects without obesity, a synchronization was observed in the diurnal variations of leptin and sweet taste recognition thresholds, which suggests a connection between both systems." (PMID 35631243, 2022). "Several studies have demonstrated that leptin and IVDD are influenced by both sex and obesity." (PMID 36293132, 2022). "Brain-specific knockdown of leptin analog in Drosophila produces obesity hallmarks, however, no skeletal muscle aspects have been examined." (PMID 36613864, 2022). "Population-based studies found that self-reported short sleep duration was associated with decreased leptin levels and increased ghrelin in blood independent of BMI, which could elevate hunger and appetite, resulting in chronically predisposing an individual to overweight or obesity." (PMID 36276399, 2022). "Hyperleptinemia in the absence of high fat diet and/or obesity improves insulin sensitivity and glucose uptake and only elicits leptin- and insulin-resistance in the context of diet-induced obesity." (PMID 35721743, 2022). "A number of these studies do not confirm the relationship between the content of leptin in breast milk and the prevalence of obesity in breastfed children." (PMID 35684517, 2022). "The lack of leptin or the leptin receptor results in obesity due to the combined effects of hyperphagia and decreased energy expenditure." (PMID 36233056, 2022). "The importance of this work must be highlighted since RYGB surgery is an effective treatment for obesity and the fact that it decreases the expression of PTP1B and produces an improvement in leptin sensitivity provides further support to the hypothesis." (PMID 35563589, 2022). "They found that obesity and diabetes due to impaired leptin signaling contribute to pathological changes in the vertebrae as well as an immature IVD phenotype, particularly in females, suggesting a sex-dependent role of leptin." (PMID 36293132, 2022). "Although metformin reduced HF diet-related obesity and retroperitoneal adiposity in dams, it did not affect serum leptin concentration." (PMID 36430717, 2022). "Leptin plasma concentrations are elevated in obesity as well as in cardiovascular diseases, independent of body weight, such as ischemic heart disease, cardiomyopathy, and congestive heart failure." (PMID 35955485, 2022).
Obesity (continued). "Thus, pharmacological drugs or natural compounds inhibiting both Leptin and GLUT-4 are highly desired for the treatment of obesity and diabetes." (PMID 35889791, 2022). "Serum leptin has been found to be significantly elevated in cases of prostate cancer and breast cancer, independent of obesity." (PMID 35628271, 2022). "The fact that leptin and LEPR are expressed in pulpal and periapical tissues could be interpreted as evidence supporting the relationship between obesity, inflammation, and endodontic infections." (PMID 35216099, 2022). "This explains why leptin has not been found to be an efficient anti-obesity therapy, due to a state of leptin resistance." (PMID 36278579, 2022). "Taken together, caloric restriction prevented obesity-induced LV hypertrophy and protected against acute IH-induced cardiac remodeling independent of leptin signaling in obese mice." (PMID 36160851, 2022). "The levels of endotoxemia and serum leptin increased in the HFD group, while in the HFD + BCP group, similar values were found to those of the STD group, attributing the ability to reduce these in conditions of obesity." (PMID 36234691, 2022). "In contrast, obesity triggers the secretion of cytokines involved in osteoporosis, negative vessel remodeling, and inflammation with increased leukemia inhibitory factor (LIF), IL1β, CCL2, leptin, interferon gamma (IFNγ), IL6, and TNFα." (PMID 36010901, 2022). "Individuals with obesity are known to have high blood levels of leptin, but their appetite is not suppressed and they are in a leptin-resistant state." (PMID 36685567, 2022). "The increased leptin levels observed in the HFD group, further confirmed the state of obesity." (PMID 36451148, 2022). "They observed that adults with obesity had a greater initial increase in TBE-specific antibody titers at day 7 to day 28, followed by a sharp decline 6 months post TBE vaccination that correlated with high BMI and leptin levels." (PMID 36466818, 2022). "In obesity, leptin resistance is produced due to the excess adiposity, and, therefore, leptin does not properly reduce food consumption, leading to increased body weight." (PMID 35057485, 2022). "We used two genetically engineered obesity mouse models, ob/ob and db/db mice, to determine the effect of obesity without leptin and its receptor in endometriosis development." (PMID 36140261, 2022). "Here, it has been suggested that LepR is not the main leptin transporter in human BBB, but rather the megalin receptor, since the authors observed a reduction in brain leptin uptake by eliminating the megalin receptor in the endothelial cells of the BBB, which induced hyperphagia and obesity." (PMID 35563589, 2022). "In other studies, green tea supplementation does not appear to affect obesity hormones, leptin, and adiponectin." (PMID 36558368, 2022). "The conducted studies on the influence of leptin on the incidence of obesity in children do not give clear results." (PMID 35684517, 2022). "The activation of the endocannabinoid system potentially contributes to hyperphagia, decreased energy expenditure, obesity and metabolic syndrome through the involvement of appetite modulators such as melanin-concentrating hormone (MCH), leptin and glucocorticoids within the hypothalamus." (PMID 35328759, 2022). "While inhibiting leptin signaling in ob−/− and DB−/− mice models resulted in obesity, it did not affect the occurrence of knee OA." (PMID 35873487, 2022). "The significant correlations between leptin with TSH and fT4 suggest that the changes in thyroid hormone are directly related to leptin independent of obesity." (PMID 35501770, 2022). "Secondly, increasing circulating inflammatory cytokines induced by obesity, such as TNF-α, and higher leptin could lead to the inflammation and fibrosis in the liver." (PMID 36387941, 2022).
Obesity (continued). "The hormone leptin secreted by the adipose cells plays a critical role in whole body energy and weight homeostasis: lack of functional leptin or leptin receptors results in severe and early onset obesity in rodents and humans." (PMID 36620608, 2022). "MS-NASH mice display ob/ob or db/db-like characteristics of spontaneous obesity and metabolic syndrome, but independent of genetic knockout of leptin or leptin receptors that are not found in humans." (PMID 36499091, 2022). "In line with our data in ob/ob mice, we also found an anorexigenic effect of LEAP-2 in ghrelin-induced food intake in another obesity model, the DIO mice, which is in clear contrast to the leptin-resistant state observed in DIO mice and highlights its potential translational relevance." (PMID 35159134, 2022). "Nevertheless, in obesity, despite high circulating serum leptin levels, a feeling of satiety remains absent." (PMID 36142638, 2022). "Leptin, GLP-2, and CCK correlations with obesity markers were annulled when adjusting for BMI." (PMID 35334929, 2022). "However, in obesity, massive secretion of leptin by adipose tissues triggers hyperleptinemia, which leads to resistance of the HPG-axis to leptin signaling, thus negatively affecting male fertility." (PMID 36225310, 2022). "A crucial note to make is that for certain blood cancers, serum leptin was elevated independent of the patient’s BMI, persuading against confounding factors such as obesity." (PMID 35628271, 2022). "Unlike Leptin, Adiponectin, an adipokine involved in energy homeostasis, is reduced in obesity and possesses anti-inflammatory properties on macrophages." (PMID 35543703, 2022). "Importantly, deletion of UCP2 in microglia is also associated with more excitatory synaptic inputs onto the POMC neurons, and this leads to increased sensitivity to leptin in POMC neurons and resistance to HFD-induced obesity in mice." (PMID 33826123, 2022). "Celastrol treatment in adult animals has also been reported to increase leptin sensitivity, ameliorate non-alcoholic fatty liver disease, and increase iWAT browning and BAT activation, which protect against diet-induced obesity." (PMID 35684076, 2022). "Leptin is an adipocytokine associated with satiety signaling and is reported to be increased during obesity without any beneficial effect on energy homeostasis, suggesting leptin resistance." (PMID 36714129, 2022). "In the context of conventional obesity, obese individuals do not lack leptin; rather, they display higher levels of circulating leptin." (PMID 35774455, 2022). "We found that leptin (50.2% of the effect of BMI on pre-eclampsia), fasting insulin (27.7%–36.6%), and ISI (19.1%–50.1%) each mediated the total genetically predicted effects of obesity traits on female reproductive disorders." (PMID 35104295, 2022). "Similarly, at the visceral adipose tissue level, HFD-induced obesity led to an up-regulation of the production of IL-1β, IL-6, TNF-α and MCP-1 as well as leptin and adiponectin." (PMID 35624723, 2022). "Many studies have shown that LEP and LEPR play an important role in obesity." (PMID 36253742, 2022). "Tumor necrosis factor-α, plasma leptin, and non-esterified fatty acid levels are all high in obesity and can impact insulin resistance and consequently diabetes mellitus." (PMID 35845804, 2022). "Nevertheless, these antibodies should not affect the central actions of leptin and consequently lead to increased obesity and hyperphagia." (PMID 35270000, 2022). "This fits well with previous data describing a negative correlation between leptin plasma levels and age in subjects with obesity." (PMID 35811457, 2022). "IR is not related to leptin and adiponectin levels, however, leptin and adiponectin levels correlate well with BMI in hypothyroid children and adolescents with obesity." (PMID 35501770, 2022).
Obesity (continued). "The stimulation of the LEP-mediated JAK2-STAT3 signaling pathway in liver and adipose tissue improves leptin resistance of obese mice, thus playing a role in the treatment of simple obesity." (PMID 35529938, 2022). "Abnormal secretion of cytokines (leptin, adiponectin, TNF-α, and IL-6) due to obesity may lead to insulin resistance in the body." (PMID 36079890, 2022). "Unlike other adipose-derived hormones like leptin and resistin, which correlate positively with obesity measures, adiponectin correlates inversely with obesity in rodents and humans." (PMID 35664415, 2022). "A major disadvantage of some of these rodent models is that they do not closely reflect human obesity, which is multifactorial and not always affecting leptin signaling, thus rendering it difficult to translate findings in these rodents to human patients." (PMID 35505192, 2022). "Combination of the SGLT2i Dapagliflozin and carbohydrate restriction in patients with T2D and obesity resulted in a significant reduction of weight, fat mass and serum leptin, with no discernible change in energy expenditure or appetite at 12 months." (PMID 36266774, 2022). "However, these phenotypes correlated with obesity/hyperphagia and protection against high-fat-diet (HFD)-induced obesity, respectively, in favor of an indirect mechanism driven by central, leptin-dependent signals." (PMID 36140242, 2022). "Our leptin results were increased in the Obesity, but without significant changes in this parameter in OR." (PMID 35951512, 2022). "After syndromic obesity was discarded by lacking dysmorphic features, leptin serum levels were measured and were very low." (PMID 34504472, 2021). "Being skewed toward a proinflammatory state, alterations in adipocyte-intrinsic cellular metabolism impacts adipocyte-immune cell crosstalk via changes in adiponectin, leptin, and IL-6, as well as other pro-inflammatory mediators (e.g., TNF, IL-1, type I IFNs, etc.)is dysregulated during obesity." (PMID 33958704, 2021). "The discovery of leptin was initially expected to ameliorate the obesity epidemic; however, this expectation has never been met." (PMID 34955895, 2021). "Although the mechanisms for obesity in BBS remains incompletely understood, disruption of the hypothalamic leptin‐melanocortin signaling pathway is evident, and BBS may provide insights into obesity in other monogenic and syndromic obesity disorders." (PMID 32700463, 2021). "In the present study, the link between plasma leptin levels and arylesterase activity was not modified by obesity." (PMID 34332593, 2021). "Leptin acts mainly by maintaining energy homeostasis: in the obesity stage, high levels of circulating leptin generate negative feedback into a specific nucleus of the hypothalamus, the regulatory organ that increases sensitivity to the satiety signal." (PMID 34868066, 2021). "It is necessary that these antibodies should not change the activity of leptin on food intake, to avoid the development of hyperphagia and obesity." (PMID 33673730, 2021). "Under these circumstances, the blockade of leptin signaling in leptin resistant obesity would treat hypertension, but would not affect metabolism or respiratory control." (PMID 34276408, 2021). "Despite leptin’s central role in regulating food intake and increased circulating levels in obesity, there were no genotype differences detected in serum leptin concentration in either the fed or 6 h fasted states." (PMID 34502525, 2021). "Another important limitation of our study was the lack of measuring inflammatory markers, leptin, as well as synovial fluids of markers that are more related to obesity-mediated joint inflammation." (PMID 33596883, 2021). "In contrast to leptin, adiponectin is recognized as an anti-inflammatory factor, strongly inhibiting lipopolysaccharide-induced production of TNF-α in macrophages, and its expression is inversely correlated with obesity." (PMID 33557311, 2021).
Obesity (continued). "In addition, as the improvement of leptin and adiponectin levels was confirmed when BSE was administered, BSE seems to be helpful in obesity-induced diabetes and dietary disorders." (PMID 34564426, 2021). "Hence, a rise in body weight, blood glucose level, serum insulin, leptin and resistin levels along with reductions in serum adiponectin levels in HFD and sucrose fed rats indicates the development of obesity induced insulin resistance in them." (PMID 33917607, 2021). "Despite the large sample size, our MR analyses do not support causal effects of circulating adiponectin, leptin, sOB‐R and PAI‐1 concentrations on the development of five obesity‐related cancers." (PMID 33038280, 2021). "After adjusting by leptin, insulin levels remained significantly higher in adolescents with obesity as compared with levels in those without obesity." (PMID 35071145, 2021). "In diet-induced obesity (DIO) protocol, mice were fed chow diet (CD) or high-fat diet (HFD) for 4 or 16 weeks, whereas in the hyperleptinemic model (LEPT), mice were injected with leptin for 16 days (16 L) or saline (16 C)." (PMID 34805147, 2021). "So it is not surprising that leptin, which is almost invariably elevated in obese patients, has been recognized as one of the adipokines mediating the pro-inflammatory state of obesity." (PMID 33804765, 2021). "Circulating leptin levels are increased in obesity and, with prolonged exposure, leptin can induce its own negative feedback loop via STAT3-dependent SOCS3 accumulation." (PMID 35111163, 2021). "Heavy-load exercise increased inflammation, counteracted leptin resistance, and did not effectively relieve the obesity-induced HH symptoms." (PMID 33472656, 2021). "Obesity is characterized by impaired leptin signaling despite elevated leptin levels, that is, leptin resistance, which explains why leptin administration to most people with obesity is not effective." (PMID 34327017, 2021). "It is well‐known that lack of leptin leads to a severe obese phenotype and deletion of its receptor also leads to obesity and diabetic traits." (PMID 34156126, 2021). "Recently, MSI-1436 has been shown to inhibit PTP1B—a key enzyme regulating insulin and leptin signaling, via a non-competitive allosteric mechanism, which improves insulin sensitivity and reduces obesity." (PMID 33536069, 2021). "Obesity is currently presented as a pro-inflammatory state with an expansion in the outflow of inflammatory cytokines, such as interleukin-6 (IL-6) and tumor necrosis factor-alpha (TNF-α), alongside the expanded emission of leptin." (PMID 33946540, 2021). "Adipocytes are important endocrine cells in the tumor microenvironment of obesity-related tumors, which can secrete a variety of adipokines (such as leptin, adiponectin, estrogen, resistin, MIF and MCP-1, etc.), among which leptin, adiponectin and estrogen are the most in-depth and valuable ones." (PMID 34485124, 2021). "It was confirmed that diet-induced obesity (DIO) mice exhibited reduced survival, increased systemic metabolic and inflammatory disorders, upregulated tumoral cancer stem cell (CSC)/EMT gene signature, and greater leptin signaling." (PMID 34350120, 2021). "In the absence of LepRb-STAT3 signalling, leptin is unable to exert its anti-obesity effects, but is still able to exert its permissive fertility effects." (PMID 34502119, 2021). "We aimed to compare leptin, ghrelin, adiponectin and insulin-like growth factor-1 (IGF-1) levels of pre-feed and post-feed breast milk in mothers with obesity and normal weight, and tried to determine their effects on infants’ growth over weight for length z-score." (PMID 34348809, 2021). "Leptin levels are higher in individuals with obesity compared to those without obesity, as well as in women compared to men." (PMID 34884416, 2021). "It appears that elevated levels of leptin result from obesity, which frequently accompanies OSA, rather than the mechanisms related to sleep disorders." (PMID 34768715, 2021).